RNU4ATAC18P (RNA, U4atac small nuclear 18, pseudogene)
Gene: Small nuclear RNA gene on chromosome 6 (159,720,415 to 159,720,540, reverse strand). Ensembl gene ENSG00000251988.
Homologues: Orthologues: chimpanzee RNU4ATAC18P (100% identical), macaque RNU4ATAC18P (86% identical). Paralogues in human: RNU4ATAC16P (86% identical), RNU4ATAC2P (82% identical), RNU4ATAC11P (81% identical).